NFYC (nuclear transcription factor Y subunit gamma)
Description:
Component of the sequence-specific heterotrimeric transcription factor (NF-Y) which specifically recognizes a 5'-CCAAT-3' box motif found in the promoters of its target genes. NF-Y can function as both an activator and a repressor, depending on its interacting cofactors.
Synonyms: NF-YC; CBF-C; CBFC; H1TF2A; HAP5; HSM
Tractability: Small molecule: a structure with a bound ligand is known. PROTAC: ubiquitination databases record sites on it; its protein half-life has been measured.
Gene: Protein-coding gene on chromosome 1 (40,691,570 to 40,771,606, forward strand). Ensembl gene ENSG00000066136.
Subcellular location: Nucleus
Subcellular location (Human Protein Atlas): Nucleoplasm
Pathways (Reactome):
Cellular responses to stimuli: ATF4 activates genes in response to endoplasmic reticulum stress; ATF6 (ATF6-alpha) activates chaperone genes
Metabolism: Activation of gene expression by SREBF (SREBP); PPARA activates gene expression
Gene expression (Transcription): FOXO-mediated transcription of cell death genes
Gene Ontology:
Molecular function: DNA binding; DNA-binding transcription activator activity, RNA polymerase II-specific; protein binding; RNA polymerase II cis-regulatory region sequence-specific DNA binding; transcription cis-regulatory region binding; DNA-binding transcription factor activity; DNA-binding transcription factor activity, RNA polymerase II-specific; protein heterodimerization activity
Biological process: positive regulation of transcription by RNA polymerase II; regulation of DNA-templated transcription; regulation of transcription by RNA polymerase II; protein folding
Cellular component: CCAAT-binding factor complex; nucleoplasm; nucleus; protein-DNA complex; RNA polymerase II transcription regulator complex; chromatin; transcription regulator complex
Genetic constraint (gnomAD): Loss-of-function variants: 21 observed, 40.86 expected, observed/expected ratio (o/e) 0.51, 90% interval 0.36 to 0.74. The upper end of that interval is the gene's LOEUF score, 0.74, which puts it in group 3 of 6, group 1 being the genes least tolerant of losing a copy. Missense variants: 204 observed, 339.8 expected, observed/expected ratio (o/e) 0.6, 90% interval 0.54 to 0.67. Synonymous variants: 118 observed, 128.41 expected, observed/expected ratio (o/e) 0.92, 90% interval 0.79 to 1.07.
Homologues: Orthologues: chimpanzee NFYC (100% identical), guinea pig NFYC (99% identical), macaque NFYC (99% identical), mouse Nfyc (99% identical), rat Nfyc (99% identical), dog NFYC (99% identical), pig NFYC (99% identical), rabbit NFYC (99% identical), tropical clawed frog nfyc (90% identical), zebrafish nfyc (87% identical), Drosophila melanogaster Nf-YC (39% identical), Caenorhabditis elegans nfyc-1 (14% identical). Paralogues in human: DRAP1 (14% identical), POLE4 (12% identical).
Diseases named in the same sentence as NFYC in open-access papers:
NFYC is named in the same sentence as 33 diseases in open-access papers, as found by Europe PMC text mining. Sharing a sentence is not in itself a finding about the gene and the disease. The quoted sentences say what the papers report.
choroid plexus carcinoma (5 papers, 2019 to 2024). A malignant neoplasm arising from the choroid plexus. "NFYC is a transcription factor that regulates the epigenome and has been identified as an oncogene in choroid plexus carcinoma." (PMID 37715537, 2024). "NFYC subunit promotes tumor growth in glioma and functions as an oncogene in choroid plexus carcinoma." (PMID 38378644, 2024). "NFYC was previously identified as an important regulator in tumorigenesis of choroid plexus carcinoma." (PMID 33816550, 2021).
prostate carcinoma (2 papers, 2018 to 2022). A carcinoma that arises from epithelial cells of the prostate gland. "NFYC has been shown to promote the growth of prostate cancer cells." (PMID 36152055, 2022). "For example, expression of miR-30c-1 is not correlated with its host gene NFYC (R = 0.06; FDR = 0.23) in prostate cancer, suggesting that it does not originate from the NFYC transcription unit." (PMID 30785618, 2018).
Huntington disease (1 paper, 2020). Huntington disease (HD) is a rare neurodegenerative disorder of the central nervous system characterized by unwanted choreatic movements, behavioral and psychiatric disturbances and dementia. "The nuclear transcription factor Y subunits NFYA and NFYC, which both contain high-scoring PrLDs affected by splicing, are sequestered in Htt aggregates in patients with Huntington’s disease." (PMID 31914925, 2020).
pancreatic adenocarcinoma (1 paper, 2020). "Using the GSE15471 and TCGA-Pancreatic adenocarcinoma (PAAD) datasets, we analyzed the clinical importance of TOP2A-associated genes (HDAC1, HDAC2, HMGB1, HMGB2, NFYA, NFYB, NFYC, and SP1)." (PMID 32977589, 2020).
pancreatic cancer (1 paper, 2020). "The transcription factors NFYC, TFDP3, POLE3 and E2F4 are closely linked to hub genes in pancreatic cancer." (PMID 32587798, 2020).
Sepsis (1 paper, 2023). Sepsis is defined as life-threatening organ dysfunction caused by a dysregulated host response to infection. "In the end, we managed to formulate a signature of 7 IRGs for the prognosis of sepsis patients: − 0.465 × CCL5 + 0.215 × DEFA4 − 1.487 × NFYC + 1.055 × ESR1 − 0.737 × TNFRSF8 − 0.228 × CX3CR1 + 1.003 × SERPINA3." (PMID 36650470, 2023). "Although little is known about the roles of NFYC, TNFRSF8 and SERPINA3 in sepsis, NFYC is characterized as a new regulator of skeletal muscle immunometabolic signaling." (PMID 36650470, 2023).
tumor (9 papers, 2019 to 2026). "NFYC promotes Akt signaling in HCC by activating MTFR2, which has a significant impact on tumor growth, metastasis, and metabolic reprogramming." (PMID 40165955, 2025). "The interaction between NFYC and KAT2A indicates that POU5F1 participates in tumor development through KAT2A‐mediated histone H3 succinylation." (PMID 32978904, 2020).
cancer (8 papers, 2019 to 2025). A tumor composed of atypical neoplastic, often pleomorphic cells that invade other tissues. "In cancer, NFYC has been shown to modulate SREBF-driven pathways, linking it to the transcriptional control of metabolic genes such as DHCR7 and SLC38A2, both of which were also observed in our model." (PMID 40941703, 2025). "Twenty genes were found mutated orwith copy number alterations in at least five percent of three cancer cohortsand six of them (PHOX2A, NFYC, EST2, EIF2S1, SSRP1 and PARP1) associated withimpacted patient survival." (PMID 32159609, 2020). "In addition, we also found significant positive correlations of gene expressions between FOXM1 and the NFY subunits (NFYA, NFYB or NFYC) in several cancer types." (PMID 32858881, 2020). "Additional cancer-relevant transcriptional regulators higher in responders before vaccination include SP2, NFYC, AKNA, MYPOP, and ZNF652." (PMID 39450169, 2024). "Its repeated appearance as an intermediary node across multiple SHAP-modulator queries suggests that NFYC may act as a shared transcriptional regulator, potentially modulating the conditional contribution of USF3 in cancer-relevant pathways." (PMID 40941703, 2025).
infection (3 papers, 2014 to 2024). The state of being infected such as from the introduction of a foreign agent such as serum, vaccine, antigenic substance or organism. "At 20°C, the expression of Ciita, NFYB, NFYC, CALR, Canx and TNF reached the peak at 24 hpi, which was significantly higher and earlier compared to 10°C infection group." (PMID 35197977, 2022).
NFYC also shares sentences with these, for which no sentence is quoted: glioma (3 papers); fungal infections (2); liver cancer (2); lung squamous cell carcinomas (2); acne (1); breast tumors (1); brucellosis (1); coronary atherosclerosis (1); cyst (1); diffuse large B-cell lymphoma (1); endometriosis (1); glioblastoma (1); hyperlipidemia (1); Hypertension (1); infectious disease (1); iron deficiency (1); lung carcinoma (1); mental retardation (1); metabolic disorder (1); neurological disorders (1); oral candidiasis (1); oral squamous cell carcinoma (1); tuberculosis (1); type 2 diabetes mellitus (1).